IRAK4 (interleukin 1 receptor associated kinase 4)
Diseases named in the same sentence as IRAK4 in open-access papers (continued):
Sharing a sentence is not in itself a finding about the gene and the disease.
inflammation (5 papers, 2016 to 2025). Aberrant reaction of the microcirculation characterized by movement of fluid and leukocytes from the blood into extravascular tissues. "We used an established murine model of acute lung inflammation, and studied human lung tissue ex vivo, to investigate the effects of inhibiting IRAK4 on lung inflammatory pathways." (PMID 39137914, 2024). "In addition, we have designed and generated a novel selective IRAK4 inhibitor that is able to reduce LPS-induced airway inflammation in wild-type mice." (PMID 39137914, 2024). "In addition, we characterize a novel selective IRAK4 inhibitor, BI1543673, and show that this compound can reduce lipopolysaccharide (LPS)-induced airway inflammation in wild-type mice." (PMID 39137914, 2024).
infectious disease (2 papers, 2009 to 2025). A disorder directly resulting from the presence and activity of a microbial, viral, or parasitic agent in humans. "The findings were found align with previous report displaying that nsSNPs in conserved regions of immune regulatory proteins, such as MyD88 and IRAK4 disrupt protein stability and function, increasing susceptibility to infectious disease." (PMID 41231851, 2025). "For instance, mutations in TLR2, TLR4, TLR5 and IRAK4 have all been associated with increased risk to develop infectious diseases." (PMID 19859543, 2009).
neurological disorders (2 papers, 2011 to 2026). "They attenuate inflammation-induced disorders such as cardiovascular and neurological disorders via down-regulating pro-inflammatory cytokines (IL-6, CRP, COX-2, LPO, TGF-β1, NF-κB, and TNF-α), and pathways (IRAK4, MAPK, JAK/STAT3, TLR4, and ERK)." (PMID 41640995, 2026). "Multivariate logistic analysis showed that IRAK4 and CypA were the proteins most associated with ALS rather than neurological disorders, with 91% discriminatory power (AUC 0.905)." (PMID 21998667, 2011).
cardiovascular disease (1 paper, 2022). "Indeed, significant overexpression of the Toll-like receptor 4 (TLR4) gene, the activation of interleukin-1 receptor-associated kinase 4 (IRAK4), in addition to numerous cathepsin proteases and matrix metalloproteinases were observed in MPS cardiovascular disease." (PMID 36556450, 2022).
hematologic cancers (1 paper, 2025). "IRAK4 inhibitor emavusertib is currently being assessed in phase 1/2 clinical studies for hematologic cancers and several solid tumors." (PMID 40338274, 2025).
IRAK4 also shares sentences with these, for which no sentence is quoted: pancreatic ductal adenocarcinoma (4 papers); Cerebral ischemia (3); hidradenitis suppurativa (3); anemia (2); auto-inflammatory syndrome (2); chronic lymphocytic leukaemia (2); chronic rhinosinusitis (2); glioblastoma (2); haematological disease (2); neurodegenerative disease (2); non-Hodgkin lymphoma (2); Shock (2); tuberculosis (2); Waldenström macroglobulinemia (2); abscess (1); adult-onset Still disease (1); Allergy (1); Anxiety (1); asplenia (1); bacteremia (1); Barth syndrome (1); brain tumor (1); bronchiolitis (1); Burkitt lymphoma (1); Cachexia (1); cervical lymphadenitis (1); Cervical lymphadenopathy (1); cholestatic jaundice (1); chronic hepatitis B virus infection (1); chronic mucocutaneous candidiasis (1).
A further 38 diseases each share a sentence with IRAK4 in 1 paper.